PON2 (paraoxonase 2)
Diseases named in the same sentence as PON2 in open-access papers (continued):
Sharing a sentence is not in itself a finding about the gene and the disease.
cardiovascular disease (17 papers, 2007 to 2025). "Examination of the association between FH and PON2 reveals that PON2 variants are implicated in the clinical presentation of cardiovascular disorder in FH patients." (PMID 32489792, 2020). "Recently, emerging evidence has proposed that PON2 is antiatherosclerotic and may be associated with cardiovascular disease (CVD)." (PMID 33562328, 2021). "PON2 gene polymorphism is associated with the incidence of cardiovascular diseases." (PMID 33968295, 2021). "The PON-1 and PON-2 genes are part of the same genetic cluster on human chromosome 7, and their respective polymorphisms—L55M, Q192R, A148G, and C311S—have been linked to the development of various metabolic disorders, particularly those related to lipid metabolism and cardiovascular diseases." (PMID 40002395, 2025). "Few literatures are available regarding on the role of paraoxonase 2 (PON2) in HF so far despite the protective role of PON2 in cardiovascular diseases." (PMID 36840500, 2023). "A previous study has found that PON2 has antioxidant and atherosclerotic protective effects in cardiovascular diseases." (PMID 36840500, 2023). "Other PON1 and PON2 polymorphisms (M55L, C-108T, R-160G, G-162A from PON1 and S311C and A148G from PON2) have been associated with cardiovascular disease." (PMID 25405733, 2014). "Another aspect of note is the paucity of information on the relationships between PON2 and PON3 gene polymorphisms and enzymatic activities vs. cardiovascular disease." (PMID 25405733, 2014). "In the past few years, the Paraoxonase multigene family (PON1, PON2, PON3) has been shown to play an important role in pathogenesis of cardiovascular disorders including coronary artery disease (CAD)." (PMID 31816846, 2019). "Paraoxonase 2 (PON2) plays a protective role in cardiovascular diseases, but the role of PON2 in HF has not been reported so far." (PMID 36840500, 2023).
infection (8 papers, 2012 to 2025). The state of being infected such as from the introduction of a foreign agent such as serum, vaccine, antigenic substance or organism. "Furthermore, we conducted secondary analyses to verify whether PON-1 and PON-2 polymorphisms and paraoxonase activity are associated with lipid and infection markers in PLWH using different antiretroviral therapies." (PMID 40002395, 2025). "In conclusion, our results could be useful to understand the metabolic alterations due to high glycemic index diets and suggest that downregulation of PON2 after exposure to high glucose could be involved in intestinal cell dysfunction and increased risk for infection." (PMID 31835890, 2019). "As the pulmonary system is a primary site of infection for P. aeruginosa, experiments using airway epithelial cells cultured from PON2-KO mice and a QS reporter strain of P. aeruginosa confirmed a two-fold increase in QS." (PMID 22824324, 2012). "Because of the limited number of samples, we were unable to conclusively show that expression of PPARγ and PON2 genes either changed or remained the same in individual patients upon infection with P. aeruginosa." (PMID 22860094, 2012). "Paradoxically, upon PAE infection and exposure to 3OC12-HSL, PON2 may serve a pro-apoptotic function that is associated with unidentified protein-protein interactions." (PMID 36653584, 2023). "Following the infection of retrovirus expressing GFP, similar GFP fluorescence intensity was detected in control- and PON2-shRNA LLC cells." (PMID 37337025, 2023). "PON2 is not secreted into the blood plasma, but is secreted into the intestinal lumen, where it is important for resistance to infections." (PMID 36653584, 2023). "Additionally, both RNA-seq and RT-qPCR outcomes demonstrated that PON2 and CFTR expression levels were notably increased in response to NDV vaccine infection in thymic tissues of chickens." (PMID 35403571, 2022). "There was one sample in the no infection group for which PON2 expression data was unavailable, leaving 12 patients in that group." (PMID 22860094, 2012). "Importantly, PON2 has activity against a range of homoserine lactone signaling molecules, including that produced by Burkholderia cepacia complex, but as none of our patients had detectable infection with this microorganism, we were unable to evaluate any associations." (PMID 22860094, 2012).
bacterial infection (5 papers, 2012 to 2024). "For example, three lactonases are present in humans: PON1, PON2 and PON3; of these, only PON2 is expressed in all tissues, and it appears to be involved in the first step of defense against bacterial infection." (PMID 32993120, 2020). "Moreover, PON2 represents a potential biotechnological enzyme for the treatment of biofilm-sustained bacterial infections and as such strategies for large-scale enzyme production are necessary." (PMID 38893310, 2024). "In peripheral tissues, the PON2 ability to modulate sensitivity to bacterial infections is considered to be part of the innate immunity of mammalians and might represent a pharmaceutical target for the prevention of bacterial infections." (PMID 33562328, 2021).
hematologic cancers (1 paper, 2023). "Recent research has revealed that PON2 is upregulated in tissues from patients with various types of solid tumors and hematologic cancers, likely due to its ability to suppress oxidative stress and evade apoptosis." (PMID 37337025, 2023).
hematologic malignancies (1 paper, 2018). "Contrariwise, hematologic malignancies are characterized by a low levelof this protein, deletions of the respective gene, and correlation of the levelof PON2 expression with a favorable prognosis." (PMID 30397533, 2018).
PON2 also shares sentences with these, for which no sentence is quoted: metabolic disease (5 papers); acute myeloid leukemia (2); cerebrovascular disease (2); lymph node metastases (2); Parkinson (2); retinopathy (2); thymus tumors (2); alcoholism (1); allergic disease (1); ANCA-associated vasculitis (1); atherosclerotic heart diseases (1); basal cell carcinoma (1); cardiac diseases (1); Cerebral ischemia (1); colon cancer (1); coronary artery atherosclerosis (1); diabetic retinopathy (1); dyslipidemia (1); essential hypertension (1); genitourinary neoplasms (1); glaucoma (1); hearing loss (1); idiopathic dilated cardiomyopathy (1); infarction (1); laryngeal carcinoma (1); liver (1); liver cancer (1); lymphoblastic lymphoma (1); metabolic dysfunction-associated steatotic liver disease (1); minimal change nephropathy (1).
A further 15 diseases each share a sentence with PON2 in 1 paper.